SKP2 (S-phase kinase associated protein 2)
Diseases named in the same sentence as SKP2 in open-access papers (continued):
Sharing a sentence is not in itself a finding about the gene and the disease.
cancer (continued). "SKP2 was not only positively correlated with the MSI and TMB of some cancers (e.g., COAD, READ, and SARC), but also positively associated with immune neoantigen count." (PMID 37308972, 2023). "The study disclosed the upregulated SKP2 expression in 15 neoplasms and decreased SKP2 expression in three cancers (p < 0.05)." (PMID 37308972, 2023). "The oncogenic property of Skp2 made it an appealing pharmacological target for cancer prevention and treatment." (PMID 37532777, 2023). "Accordingly, recent studies have shown SKP2 is a promising target for cancer therapy, and a few studies, including our own, have demonstrated successful pharmacological inhibition of SKP2 in preclinical cancer models." (PMID 35169199, 2022). "In the PPI networks, we identified four key molecules (PAI1, CDC20, P21, and SKP2) whose expressions were dysregulated the HBx mutants in the two human cancer cell lines." (PMID 35223517, 2022). "Intriguingly, our study showed that SKP2 expression negatively correlated with MLN4924 IC50 values in almost all cancer types." (PMID 35685435, 2022). "The F-box protein Skp2, a component of RING E3 ubiquitin ligases, was significantly correlated with several cancer-associated signaling pathways, including proliferation, cell cycle progression, migration, and invasion of cancer cells." (PMID 36385010, 2022). "To demonstrate the functional relevance of Skp2 in modulating MLN4924 sensitivity, we firstly assessed the expression of SKP2 in pan-cancer cell lines from the CCLE dataset." (PMID 35685435, 2022). "Skp2 regulates the proliferation, apoptosis, migration, invasion, angiogenesis, and metastasis of cancer cells." (PMID 36552825, 2022). "In normal cells, SKP2 mainly localizes in the nucleus, while during cancer progression, SKP2 translocates to the cytoplasm, an observation that strikingly parallels its localization (primarily cytoplasmic) in jck kidney tubular epithelial cells." (PMID 36326820, 2022). "Further, we explored the association between SKP2 expression and MLN4924 IC50 values in human cancer cell lines and pan-cancer." (PMID 35685435, 2022). "Here we found elevated SKP2 expression was consistent in tumor tissues versus normal tissues in 29 types of human common cancer in pan-cancer analysis." (PMID 35685435, 2022). "To better understand the role of Skp2 played in pan-cancer, we firstly compared the SKP2 expression using the data from TCGA and GTEx databases." (PMID 35685435, 2022). "Inhibition of Skp2 expression can effectively lead to growth cycle arrest of cancer cells and induce apoptosis." (PMID 35845132, 2022). "Beyond P27, SKP2 also regulates Cyclin E1, an established oncoprotein whose overexpression leads to cell cycle defects that promote cancer development and progression." (PMID 36496990, 2022). "Our analyses highlighted the potential role of YAP in the cancer cell proliferation of various cancers and revealed that Skp2 as the target of YAP promoted tumor cell proliferation in pan-cancer." (PMID 35685435, 2022). "Susceptibility of cancer cells to CHK1 inhibitors is fine‐tuned by cellular levels of the cyclin dependent kinase inhibitor, p27, and its degrader, SKP2." (PMID 35673965, 2022). "Last, we aimed to prove that the SKP2‐p27 axis also regulates the sensitivity of human cancer cells to CHK1‐induced apoptosis." (PMID 35673965, 2022). "We suggest that targeting Skp2, an upstream regulator for Akt, can be another potential approach for human cancer treatment on the basis of the findings from our group and others that Skp2 is required for cancer development in diverse genetic tumor models." (PMID 36180910, 2022).
cancer (continued). "In this study, we provided considerable evidence to show that an anti-microtubule agent, ABT-751, induced profound anti-cancer effects, specifically the upstream cytostasis through the inhibition of SKP2 mRNA and its corresponding protein levels." (PMID 33478005, 2021). "An example is that the screening of Skp2 E3 ligase inhibitors is to increase the p27Kip1 stability and prevent cancer growth." (PMID 33336885, 2021). "It was reported that Skp2 is highly expressed at protein and mRNA levels in a variety of cancer tissues and mediates tumorigenesis." (PMID 34702937, 2021). "As with SKP2, there is a trend for arginine substitutions to occur across a diverse array of cancer types (bladder; colorectal; head and neck; stomach; uterine)." (PMID 35008511, 2021). "In support of the oncogenic role of SKP2, pharmacological inhibition of SKP2 was found to be able to restrict cancer progression." (PMID 33130827, 2021). "Collectively, these data suggest that, under normal conditions, βTrCP and SKP2 expression and function are tightly regulated to maintain accurate cell cycle progression, ensure genome stability, and prevent cancer development." (PMID 34445249, 2021). "SKP2, a critical component of the SCFSkp2 ubiquitin ligase complex, is frequently overexpressed in many human cancers." (PMID 34366863, 2021). "SKP2, a well-characterized F-box protein, acts as a classic oncogene by promoting proliferation and survival of cancer cells, mainly through targeted degradation of numerous tumor suppressive proteins, including p2133 and p2734,35." (PMID 33628597, 2021). "The Akt/mTORC1/eIF4E axis regulates Skp2 mRNA translation during escape from contact inhibition exit (one of the hallmarks of cancer cells) and restores Skp2 oncogenic transformation." (PMID 34068643, 2021). "We found that co-culture with normal cells significantly suppressed the growth of cancer cell clusters through the activation of Akt-Skp2 pathway." (PMID 33793628, 2021). "Many other molecules have reduced SKP2 expression in cancer cells, including SZL-P1-41, longikaurin A, curcumin, and other natural compounds." (PMID 34203106, 2021). "Screening for the impact of other amplified cancer genes in HEK293 cells also demonstrated that EGFR, AKT2, CCND1, CCNE1, SKP2, and FGFR3 caused both increased abundance of phosphorylated ZFP36/TTP and ARE-post-transcriptional reporter activity." (PMID 34535639, 2021). "We found that the more the cancer cells expressed SKP2, the more tumoral FOXP3 was significantly expressed." (PMID 34414959, 2021). "Specifically, SKP2 is a well-defined oncoprotein and was found to be overexpressed in various human cancers." (PMID 33130827, 2021). "Several Skp2 inhibitors including compound 25, compound A, and compound C exhibit significant anti-growth/tumor effects in cancer cells and mouse models." (PMID 33670113, 2021). "Curcumin has been shown to suppress several cancer-related kinases, including AMP-kinase, S-phase kinase-associated protein 2 (Skp2) pathway, mitogen-activated protein kinase (MAPK) (p38, ERK) and AKT/protein kinase B (PKB)." (PMID 34959384, 2021). "Across a range of cancer types, mRNAs encoding NUCKS1 and SKP2 display a significant positive correlation." (PMID 34845229, 2021). "Compound A; SMIP004; and the compounds C1, C2, and C3 are small-molecule SKP2 inhibitors that have been shown to stabilize p27 in various preclinical cancer models." (PMID 34203106, 2021). "The E3 ligase Skp2 has been reported to overexpress in many human cancers and can regulate tumorigenesis, further supporting that Skp2 is a possible target for tumor drugs development." (PMID 35006464, 2021). "The downregulation of SKP2 by curcumin treatment inhibited tumour growth, migration, and invasion in multiple cancers, including PCa." (PMID 34366863, 2021). "In particular, therapeutically targeting SKP2, which is overexpressed in a variety of cancers, has exciting potential to capitalize on MYC’s pro-apoptotic function." (PMID 34178666, 2021).
cancer (continued). "Both Skp2 and Slug are associated with the process of EMT, which can contribute to chemotherapy resistance in various cancers." (PMID 33799604, 2021). "SKP2 is a well-recognized F-box protein; it is repeatedly overexpressed in several human carcinomas and impacts in tumorigenesis." (PMID 33478005, 2021). "The FOXO1 protein is polyubiquitinated by E3 ligases such as S-phase kinase-associated protein 2 (SKP2) and mouse double minute 2 homolog (MDM2), and targeted for protein degradation in human primary tumors and cancer cell lines." (PMID 31936903, 2020). "Skp2, a member of F-box proteins, was involved in coordinating the G1/S transition and cancer progression." (PMID 33392189, 2020). "Further gain- or loss-of-function studies are required to determine the effect of safranal on PI3K/AKT signaling and NF-κB pathway in regulating cancer recurrence in relation to Skp2 suppression." (PMID 33392189, 2020). "Given the potential role of SKP2 in cancer stem cells, elucidating SKP2-dependent versus SKP2- and p27Kip1- independent mechanisms will provide insights into the mechanisms of cancer cells resistance and relapse." (PMID 31772299, 2020). "The significant down-regulation of genes in all subsystems of the viral carcinogenesis pathway indicate the inhibitory effect of the V3 treatment on many viral induced cancer hallmarks, e.g. down-regulation of proliferation by SKP2 in the Epstein-Barr virus." (PMID 32228434, 2020). "SKP2 has also been demonstrated to display an oncogenic function since it’s over expression has been observed in many human cancers including CRC." (PMID 32856866, 2020). "When ROC-1 is overexpressed specially in the nucleus skp2 of SCF complex recognizes and promotes degradation of p21 or p27 proteins and in turn causes cell unregulated proliferation, a primary alteration in cancer cells." (PMID 32264924, 2020). "SKP2 is an important oncogene and is widely overexpressed in various cancers, such as breast cancer and hepatocellular carcinoma." (PMID 33643919, 2020). "Several studies demonstrated that SKP2 functions as an oncogene and is overexpressed in cancer including hematological neoplasms." (PMID 32674429, 2020). "Skp2 has been found to positively regulate cancer stem cell populations and has self-renewal ability." (PMID 32961800, 2020). "Additional biological studies and structure modifications will further improve the potency of SKP2 inhibitors for eventually reaching clinical applications in cancer therapies." (PMID 32674429, 2020). "Overexpression of Skp2 has been reported in the majority of human cancers, including mammary malignancy." (PMID 32626765, 2020). "Given the roles of SKP2 in carcinogenesis and cancer progression, inactivation of SKP2 is a potentially promising approach to cancer treatment." (PMID 32429232, 2020). "The E3 ubiquitin ligase SKP2 regulates cancer progression by targeting several tumor suppressors and many studies have documented its involvement in several cancers, including hematological malignancies." (PMID 32674429, 2020). "Previous reports have indicated that Skp2 proteins were increased in several cancer cell lines and acquired proto-oncogenic potential from the coexpression of constitutively active H-RasG12V oncogenes." (PMID 32313103, 2020). "In this study, 20(S)-Rh2E2 most probably reduces cancer cell metabolism, thereby, arresting cancer cell growth in the S-phase via Skp2 signaling as observed." (PMID 32796841, 2020). "S-phase kinase-related protein 2 (Skp2) is a key cell cycle regulator, which recently has been suggested as an important therapeutic target for cancers." (PMID 31038581, 2019).
cancer (continued). "Recently, S-phase kinase-related protein 2 (SKP2) has been reported as a key cell cycle regulator, and has functioned as an oncoprotein in a variety of human cancer cells." (PMID 31357480, 2019). "To further ascertain the role of Skp2 in cancer stem-like cells, we decided to knock down Skp2 expression in DU 145 mesenchymal cells (DU 145 SKP2 KD cells) and to analyze their tumorigenic capacity in vitro and in vivo." (PMID 30952903, 2019). "In conclusion, our data confirm that Skp2 silencing decreases the tumorigenic potential of mesenchymal DU 145 cells and affects the functional properties of cancer stem-like cells." (PMID 30952903, 2019). "High expression levels of CDK2, SKP2 and CDC25A are detected in several types of cancer, BC included, and implicated in the promotion of cancer cell proliferation." (PMID 31107884, 2019). "Recently, several reports demonstrated that SKP2 is involved in autophagy activation for promoting cancer cell proliferation and survival." (PMID 31357480, 2019). "Overexpression of SKP2 is frequently observed in cancer progression and metastasis, and recent studies have demonstrated that SKP2 behaves as an oncogene." (PMID 31357665, 2019). "Although SKP2 is an important regulator that has been widely studied in various cancer types, the role of SKP2 in HBV-infected HCC has rarely been analyzed." (PMID 31357665, 2019). "And as a result, a cohort of APCCdh1 substrates, including Plk1, Cdc6, Skp2, cyclin A, are eliminated, which eventually helps to amplify and sustain the anti-cancer function of these inhibitors." (PMID 31420536, 2019). "Several studies have confirmed that p27 is a primary target substrate of SKP2 and that its expression is inversely related to SKP2 expression in human cancers." (PMID 30999935, 2019). "Many studies have reported that SKP2 is overexpressed in various cancers of different organs, including the liver, colon, breast, prostate, and stomach." (PMID 30967999, 2019). "The Ras homolog gene family, member A (RhoA) GTPase is crucial for cancer metastasis, and RhoA transcription is regulated by the Skp2 complex." (PMID 29743060, 2018). "Various studies have demonstrated that targeting Skp2 in various cancer cells as well as in animal models resulted in the upregulation of p27 level that results into tumor shrinkage and apoptosis." (PMID 29479529, 2018). "SKP2 is deregulated and correlated with poor prognosis in a wide array of human cancers including breast, prostate, colon, lung, brain, gastric, and blood." (PMID 29594129, 2018). "It is interesting to note that all six top-ranked genes proposed to be cancer-associated (PLK1, MCM2, MCM3, MCM7, MCM10 and SKP2) were downregulated by MP-HX in both cell lines." (PMID 30042885, 2018). "siRNA mediated knockdown of Skp2 in FaDu and SCC090 cell lines depicts that curcumin strongly inhibits the growth of cancer cells via inactivation of Skp2 mediated degradation of CDKIs p27 and p21 most likely by apoptosis." (PMID 30333956, 2018). "Potential of the role of Skp2 in the sequential and stepwise development of cancer is well elucidated." (PMID 30333956, 2018). "Previous studies have demonstrated that microRNAs such as miR-186 and miR-340 can inhibit cancer cell proliferation and induce apoptosis by targeting the Skp2 pathway." (PMID 29743060, 2018). "Even though there are many reports that Skp2 inhibits apoptosis in cancer cells, our result is contradictory." (PMID 29415439, 2018). "Conversely, Skp2 is found to be overexpressed in numerous human cancers, reflecting its crucial role in oncogenesis." (PMID 29360760, 2018). "In previous studies, microRNAs have been reported to inhibit cancer cell proliferation and induce apoptosis by targeting the skp2 pathway." (PMID 29743060, 2018).
cancer (continued). "Subsequently, p-STAT3 can induce the downstream target genes, such as CCL2, CCL5, ICAM-1, SNAI1, chitinase-3-like 1 (CHI3L1), FBJ murine osteosarcoma viral oncogene homolog (FOS), and Skp2, that promote various cellular processes for cancer progression." (PMID 28157698, 2017). "Several SRs, for example, members of the F-box protein family, such as Skp2, β-TrCP, Fbw7 and Fbxl3, were shown to play significant roles in cancer and other diseases." (PMID 28861005, 2017). "Studies have reported that STAT3 interacts with the Skp2 pathway to regulate the motility and invasion of cancer cells." (PMID 29207614, 2017). "Secondly, our data also provide a new view on cancer therapy by preventing the phosphorylation of Skp2." (PMID 28446188, 2017). "The oncoprotein, namely, SKP2, which functions as a key regulator in the G1-S transit of the cell cycle, is often overexpressed in human cancer." (PMID 28337249, 2017). "SKP2 is an oncogene and is overexpressed in many human tumors in different organs; examples of such cancers are esophageal, prostate, breast, stomach, and colon." (PMID 28178195, 2017). "p27 levels were also up-regulated in rapamycin-sensitive cells Therefore, clarifying the mechanism how mTORC1 regulates Skp2 has important implications for cancer therapy." (PMID 28446188, 2017). "Since the Skp2-dependent degradation of p27kip protein obligates cancer cells to grow progressively, we checked the effect of GGpp depletion on Skp2-mediated p27kip protein degradation." (PMID 29236027, 2017). "Other prior research has demonstrated that STAT3 interacts with the Skp2 pathway to activate the motility and invasion of cancer cells." (PMID 28157698, 2017). "Collectively, our data show that the β-TrCP-FBXW2-SKP2 axis forms an oncogene-tumour suppressor-oncogene cascade to control cancer cell growth with FBXW2 acting as a tumour suppressor by promoting SKP2 degradation." (PMID 28090088, 2017). "Given the important role of Skp2, p21 and p27 regulation for cancer cell proliferation, survival and invasion, future research on the molecular connection between Skp2 regulation and RalGPS2 is warranted for new avenues of intervention." (PMID 27149377, 2016). "Previous study showed inhibitor of SKP2 displayed potent effects to decrease cancer cell viability, but only slightly decreased cell viability of normal epithelial cells." (PMID 27317767, 2016). "Taken together, Rh2E2 arrests LLC-1 cancer cell growth in the S-phase by up-regulation of p27 via abating the skp2 autoinduction loop." (PMID 26799418, 2016). "We performed the receiver operating characteristic (ROC) curve of SKP2 expression in cancer cells for recurrence of cancer analyzed in our study, the area under the curve was 0.821, indicating very good discrimination." (PMID 27317767, 2016). "Cdh1-kd led to increased proportion of S phase cells confirming previous results in other cancer cell lines compared to a decrease when Skp2 was depleted." (PMID 27374082, 2016). "Skp2 inhibitor has anti-cancer effect in various animal models and cooperates with chemotherapeutic agents to reduce cancer cell survival." (PMID 26799418, 2016). "CKS1 supports hepatocarcinogenesis by NF-κB-mediated regulation of IL-8 expression, broadening the function of Cks1 in cancer beyond its role as a Skp2 cofactor in p27 ubiquitination." (PMID 27270326, 2016). "SKP2 gene silencing using small inference RNA (siRNA) in many cancer cell lines has led to the accumulation of p27Kip1, p21waf1 expression and inhibited cell growth and survival via cell cycle arrest and induction of apoptosis." (PMID 26956626, 2016). "For example, the E3 ligase Skp2, a critical factor in cell-cycle progression, restricted cancer progression and metastasis." (PMID 27172794, 2016).